BDNF (brain derived neurotrophic factor)
Diseases named in the same sentence as BDNF in open-access papers (continued):
Sharing a sentence is not in itself a finding about the gene and the disease.
cystitis (continued). "We examined the inflammatory mediators, BDNF, NGF, VEGF, IL-6, and CCL2, and signaling kinases, pERK and pAKT, in the urinary bladder and LP, due to their established involvement in CYP-induced cystitis." (PMID 35528149, 2022). "Here, we examine inflammatory mediators (e.g., NGF, BDNF, VEGF, CCL2, IL-6) previously shown to increase expression and exhibit functional effects in micturition pathways in rodent models of CYP-induced cystitis." (PMID 35528149, 2022). "Prevention by oral gavage of imatinib reduced VEGFaa, VEGFab, BDNF, IL-6 and CCL2 mRNA, and VEGF and IL-6 protein expression in the LP and whole bladder, respectively, in mice with acute CYP-induced cystitis." (PMID 35528149, 2022). "TrkA inhibition improved bladder function in the chronic cystitis condition as well, while findings resulting from p75NTR and TrkB inhibition provide further insight into the roles of NGF and BDNF signaling in sustained conditions of bladder inflammation." (PMID 37701182, 2022). "We administered exogenous BDNF by intrathecal injection for a more in-depth exploration of the role of BDNF in neuropathic inflammation and pathological pain of CYP-induced cystitis." (PMID 31931832, 2020). "We found that BDNF immunoreactivity (green cells) was co-localized with p-Akt (red cells) in L6 DRG in cystitis." (PMID 24303055, 2013). "In the present study we show that sequestration of endogenous NGF in a cystitis rat model also blocks BDNF mRNA and protein levels in the DRG supporting a role of NGF in regulating BDNF expression in vivo." (PMID 24303055, 2013). "So far we have found that BDNF expression was regulated by endogenous NGF and also by PI3K-dependent Akt activation in L6 DRG during cystitis." (PMID 24303055, 2013). "Imatinib prevention by oral gavage (250 mg/kg) significantly (p ≤ 0.05) decreased VEGFaa, VEGFab, IL-6, CCL2 and BDNF LP mRNA but did not affect NGF LP mRNA in mice with 4 h CYP-induced cystitis (1.6–6.5-fold)." (PMID 35528149, 2022). "Furthermore, we conducted an immunofluorescence double staining assay to evaluate the localization of BDNF and p-TrkB in the SDH of the cystitis model." (PMID 31931832, 2020). "This study aimed to confirm whether BDNF-TrkB signaling modulates neuroinflammation and mechanical allodynia in CYP-induced cystitis and determine how it occurs." (PMID 31931832, 2020). "We conducted a Western blot analysis to measure the expression of BDNF-TrkB signaling in the SDH, and found that BDNF, TrkB, and p-TrkB were upregulated on days 8, 12, and 17 after the first CYP injection in the group with cystitis." (PMID 31931832, 2020). "Quantitative PCR was used to determine NGF, BDNF and receptors (TrkA, TrkB, p75NTR) and PACAP/VIP and receptors (PAC1, VPAC1, VPAC2) transcripts expression in LUT tissues from NGF-OE and WT mice with CYP-induced cystitis (4 h, 48 h, and chronic)." (PMID 29255407, 2017). "Besides, the intrathecal injection of exogenous BDNF further decreased the mechanical withdrawal threshold, promoted activation of astrocytes and microglia, and increased the release of TNF-α and IL-1β in the SDH of our CYP-induced cystitis model." (PMID 31931832, 2020). "However, whether and how BDNF-TrkB signaling in the SDH regulates neuroinflammation and mechanical allodynia in cystitis remains unknown." (PMID 31931832, 2020). "BDNF immunoreactivity was expressed in small- to medium-sized DRG neurons with a number of 85.01 ± 10.75 cells per mm2 area in control animals and a number of 171.00 ± 21.27 cells per mm2 area in animals treated with CYP, resulting in a 2-fold increase in cystitis when compared to control (p<0.05)." (PMID 24303055, 2013). "Studies have shown that BDNF may promote the activation of astrocytes and microglia through the BDNF-TrkB- p38/JNK signaling pathway, releasing large amounts of pro-inflammatory factors, which consequently exacerbate the neuroinflammatory and mechanically abnormal pain of cystitis." (PMID 38389561, 2024).
cystitis (continued). "Imatinib treatment via transurethral bladder infusion did not significantly affect CCL2, IL-6, BDNF, NGF, VEGFaa or VEGFab LP mRNA or urinary bladder protein expression in female mice with 4 h CYP cystitis." (PMID 35528149, 2022). "mRNA expression was not significantly different in mice with 4 h CYP-induced cystitis pre-treated with imatinib, compared to control (no CYP) groups, except for VEGFaa and BDNF." (PMID 35528149, 2022). "Moreover, it has been shown that brain-derived neurotrophic factor (BDNF) participates in the regulation of neuroinflammation and pathological pain through BDNF-TrkB signaling; however, whether it plays a role in cyclophosphamide (CYP)-induced cystitis remains unclear." (PMID 31931832, 2020). "Unexpectedly in the present study, NGF mRNA and BDNF mRNA and protein expression were not significantly different in mice with 4 h CYP-induced cystitis that subsequently received transurethral intravesical saline infusion compared to controls (no CYP, intravesical saline infusion)." (PMID 35528149, 2022).
melanoma (20 papers, 2008 to 2025). A malignant, usually aggressive tumor composed of atypical, neoplastic melanocytes. "The SNPs rs215605 in the PDE1C gene and rs6265 in the BDNF gene significantly interacted with smoking status on melanoma risk (interaction P = 0.005 and P = 0.003 respectively)." (PMID 27344179, 2016). "More interestingly, in situ melanoma showed a correlation with BDNF expression negativity whereas melanoma metastases were associated with BDNF immunopositivity entrusting to defects in the BDNF signaling pathway the potential ability to link these three diseases." (PMID 39267741, 2024). "IL-8, osteopontin and BDNF can be produced by melanoma cells and various type of tumor-associated stromal cells and can act in paracrine and autocrine fashion, promoting cancer cell proliferation and invasiveness, an immunosuppressive microenvironment and angiogenesis." (PMID 39143551, 2024). "In melanoma, BDNF positivity was found to be higher in metastases than in primary tumors, where it resulted associated with the presence of ulceration and higher Clark level, Breslow thickness and disease stage." (PMID 39143551, 2024). "Here, plasma levels of IL-8, CCL4, osteopontin, LIF and BDNF were determined at baseline (T0), after 2 months of therapy (T2) and, when feasible, at progression (TP), in 70 melanoma patients treated with BRAF and MEK inhibitors." (PMID 39143551, 2024). "According to studies in the EE model, enhanced BDNF levels were reported to enhance NK cell maturation and cytotoxic function against melanoma and pancreatic adenocarcinoma." (PMID 38721229, 2024). "Activation of neurotrophic factors, including the recently identified neoneurogenesis mediator BDNF, is evident during melanoma progression." (PMID 33339112, 2020). "This was manifested by the upregulation, in aggressive melanoma states, of key neurotrophic factors, including BDNF, which was recently shown to foster neoneurogenesis." (PMID 33339112, 2020). "These melanoma cells express high levels of the neurotrophic factor brain-derived neurotrophic factor (BDNF), and inhibition of either BDNF or NGFR enhances sensitivity to T cell-mediated tumor killing." (PMID 32770055, 2020). "Brain-derived neurotrophic factor was only marginally increased, melanoma antigen recognized by T cells 1 showed inverse correlation with CD271 and neurotrophins." (PMID 28112719, 2017). "In one study of melanoma in mice, researchers observed BDNF‐mediated apoptosis and demonstrated that this process could inhibit melanoma cell self‐renewal by inducing cell cycle arrest and suppressing cell proliferation." (PMID 39648800, 2024). "Importantly, concomitant TrkB and BDNF expression has been demonstrated in melanoma specimens, suggesting that the BDNF/TrkB pathway can support an autocrine loop of growth and progression in this tumor." (PMID 39143551, 2024). "Research using an enriched environment (EE) eustress model that can induce social, physical, and cognitive stimulation, unlike standard environments (SE) commonly used in biomedical research, has shown that BDNF expression induced by EE inhibits tumor progression in melanoma and colon cancer models." (PMID 38721229, 2024). "However, further studies in a larger cohort of patients are required to better define the potential of circulating BDNF as biomarkers of OS in melanoma patients undergoing targeted therapy." (PMID 39143551, 2024). "We previously showed that BDNF or TrkB could play a role as biomarkers for reduced survival in other malignancies, such as oral squamous cell carcinoma and melanoma, and this was further demonstrated in other adenocarcinomas, such as breast and lung." (PMID 33255325, 2020). "Since melanoma metastases express BDNF more frequently than primary melanomas, we checked whether BDNF would be expressed in MeLiM metastases." (PMID 18442364, 2008).
melanoma (continued). "Melanoma cells can express neurotrophic factors, such as the nerve growth factor (NGF) and brain-derived neurotrophic factor (BDNF), and their corresponding Tyrosine kinase receptors (TrkA and TrkB) that can be detected by immunohistochemistry." (PMID 40806192, 2025). "Compared to the control group, melanoma patients had higher levels of VEGF-A, PDGF-BB, IL-1RA, PIGF-1, IFN-γ, TNF-α, MIP-1α, and SCF, but lower levels of BDNF, SDF-1α, MCP-1, Eotaxin, EGF, and IL-7." (PMID 33574842, 2021). "Decreased concentrations of BDNF, SDF-1α, MCP-1, Eotaxin, and EGF were observed in primary melanoma and metastatic melanoma patients compared to healthy subjects." (PMID 33574842, 2021). "In contrast, lower concentrations of BDNF, SDF-1α, MCP-1, Eotaxin, EGF, and IL-7 were observed in the serum of melanoma patients compared to healthy controls." (PMID 33574842, 2021). "In this study, melanoma patients showed higher levels of VEGF-A, PDGF-BB, IL-1RA, PIGF-1, IFN-γ, TNF-α, MIP-1α, and SCF, but decreased levels of BDNF, SDF-1α, MCP-1, Eotaxin, EGF, and IL-7 than those in healthy patients." (PMID 33574842, 2021). "With these in mind, we searched for molecular signs of neoneurogenesis in melanoma by estimating the levels of NGF, NGFR and BDNF, in conjunction with invasive phenotypes." (PMID 33339112, 2020). "siRNA silencing or Trk inhibitors prevented BDNF-mediated expression of EMT transcription factors and affected melanoma sphere-forming potential." (PMID 31812953, 2019). "Similarly, nerve growth factor receptor (NGFR) induces brain-derived neurotrophic factor (BDNF), which allows melanoma cells to evade T cell killing mechanisms, supporting tumor progression." (PMID 40872475, 2025). "Expression of BDNF has been documented in benign pigment cell lesions and melanomas but not in normal skin." (PMID 39143551, 2024). "To test whether NGF altered the proliferation of C8161 metastatic melanoma cells, we measured changes in proliferation in co-culture experiments with NGF, BDNF, CXCL12 and NT3 by BrdU incorporation (30-min pulse)." (PMID 29175861, 2018). "The negative correlation of BDNF highlights its protective role during melanoma development." (PMID 33574842, 2021). "No BDNF expression was found in melanoma cells of MeLiM metastases (data not shown)." (PMID 18442364, 2008). "Furthermore, a cDNA array comparing three primary melanomas and three melanoma metastases with NHEM showed that NGF, NT-3, NT-4, BDNF, and NRN1-like are not differentially regulated and only NRN1 is ~48-fold elevated in melanoma compared to NHEM." (PMID 27901477, 2017).
postpartum depression (20 papers, 2015 to 2025). A type of clinical depression that occurs after childbirth. "Two studies have also investigated the association of the BDNF val66met gene polymorphism (rs6265) with postnatal depression in mothers." (PMID 34989854, 2022). "Thus, timosaponin B-III demonstrated protective effects against postpartum depression, possibly mediated by the modulation of inflammatory cytokines, the activation of the BDNF pathway, and the regulation of proteins associated with synaptic plasticity." (PMID 40566596, 2025). "- A decrease in E2 reduces BDNF transcription and translation, significantly increasing the risk of perinatal and postpartum depression.- BDNF levels positively correlate with E2, peaking during ovulation and potentially restored through hormone replacement therapy (HRT)." (PMID 39935532, 2025). "In the women that had already recovered from postpartum depression, BDNF concentration increased at 6 weeks after delivery compared to levels during pregnancy." (PMID 34989854, 2022). "Recent findings that BDNF may mediate response to dexmedetomidine in postpartum depression reinforce its potential utility as a biomarker." (PMID 41440970, 2025). "Moreover, Lactobacillus casei exerted anti-depressive effects on postpartum depression via changing the composition of gut microbiota, increasing the expression level of BDNF, and suppressing the activity of the BDNF–MAPK pathway." (PMID 36358502, 2022). "The relationship between BDNF and oxytocin has been noticed; lower BDNF and oxytocin levels are correlated to the impairment of maternal behaviors and the symptoms of postpartum depression, suggesting coordination of BDNF and oxytocin in the regulation of behavioral outcomes at postpartum." (PMID 34576011, 2021). "In addition, via modifying the gut microbiota, elevating BDNF expression, and inhibiting BDNF–MAPK pathway activity, Lactobacillus casei had antidepressive effects on postpartum depression." (PMID 39459643, 2024). "The authors reported a higher BDNF plasma concentration in the pregnant group compared with nonpregnant controls and a lower concentration in the postpartum depression group compared with the nondepressed group." (PMID 34989854, 2022). "A prior study has revealed that the elevation of BDNF expression via the ERK/CREB signaling pathway in the hippocampus correlated with increased sucrose preference, locomotor activities, and a reduction in the immobility duration in the water for a mouse model of postpartum depression." (PMID 39203778, 2024). "However, there have been no studies investigating the potential role of BDNF in postnatal depression in fathers." (PMID 34989854, 2022). "However, the authors noted that women with postpartum depression and suicidality had statistically significantly lower mean BDNF levels as compared to women without postpartum depression and suicidality (1.50 ± 1.38 vs. 2.32 ± 1.28 ng/ml, p = 0.026)." (PMID 25886523, 2015).
rheumatoid arthritis (20 papers, 2009 to 2024). A chronic, systemic autoimmune disorder characterized by inflammation in the synovial membranes and articular surfaces. "Elevated serum levels of BDNF were found in some autoimmune diseases, such as Sjögren’s syndrome, systemic lupus erythematosus, and rheumatoid arthritis, and altered serum levels of BDNF was associated with disease activity or medication used in patients with these diseases." (PMID 35009001, 2022). "The aim of this study is to investigate the role of brain-derived neurotrophic factor (BDNF) in the inflammatory responses in patients with rheumatoid arthritis (RA)." (PMID 33673283, 2021). "Some studies are manifested that high BDNF mRNA expression levels have been detected in the synovial fluid cells of osteoarthritis, rheumatoid arthritis, and spondyloarthritis patients." (PMID 30143695, 2018). "In agreement with our findings, BDNF was found in high levels in the plasma of patients with osteoarthritis and in patients with rheumatoid arthritis." (PMID 25587209, 2014). "BDNF also plays an important role in rheumatoid arthritis (RA), an autoimmune inflammatory disease." (PMID 38721229, 2024). "In subjects with rheumatoid arthritis, therapy with infliximab decreased the BDNF level." (PMID 36984890, 2023). "Recently, BDNF was suggested to play a role in the pathogenesis of rheumatoid arthritis." (PMID 35009001, 2022). "In our previous report, we found that serum BDNF was elevated in patients with rheumatoid arthritis and BDNF could promote IL-2, IL-17, and IFN-γ expression in Jurkat cells." (PMID 35009001, 2022). "Indeed, NGF is expressed in endothelial cells and keratinocytes in patients with psoriasis, and NGF and BDNF are present in the inflamed joints of patients with rheumatoid arthritis." (PMID 25418464, 2014). "Interestingly, anti-TNF-α treatment in patients with rheumatoid arthritis results in decreased plasma BDNF." (PMID 21958434, 2011). "Indeed, serum BDNF levels have been reported to be increased in autoimmune diseases such as rheumatoid arthritis and primary Sjögren's syndrome independently of immunosuppressive treatment." (PMID 21085492, 2010). "Brain-derived neurotrophic factor (BDNF), a neuromodulator involved in nociceptive hypersensitivity in the central nervous system, is also expressed in synoviocytes of osteoarthritis (OA) and rheumatoid arthritis (RA) patients." (PMID 22715356, 2012). "Concerning rheumatoid arthritis, to our knowledge, the correlation between NGF, BDNF and anti-cyclic citrullinated peptide has not been previously studied." (PMID 24223945, 2013).